IL1B (interleukin 1 beta)
Diseases named in the same sentence as IL1B in open-access papers (continued):
Sharing a sentence is not in itself a finding about the gene and the disease.
sporotrichosis (2 papers, 2016 to 2018). The commonest and least serious of the deep mycoses, characterized by nodular lesions of the cutaneous and subcutaneous tissues. "In murine models of sporotrichosis, the peptide-rhamnomannan is involved in the anti-inflammatory response diminishing the production of IL-1β and TNF-α, and in in vitro lymphoproliferation assays have shown that it contains components with different mitogenic activities." (PMID 27051673, 2016). "Also, a lipid antigen has been shown to decrease the production of proinflammatory cytokines such as TNF-α, IL-1β, and also IL-12 and IL-10 in experimental models of sporotrichosis; moreover, it is capable of inhibiting macrophage phagocytosis in in vitro assays." (PMID 27051673, 2016). "With higher levels of IFN-β, IL-17A and IL-1β and increased numbers of CD4+ T cells in the lymph nodes and spleen, ZR8 peptide is the best vaccine candidate against subcutaneous sporotrichosis." (PMID 29520092, 2018).
staphylococcal pneumonia (2 papers, 2013 to 2015). Pneumonia caused by infections with bacteria of the genus staphylococcus, usually with staphylococcus aureus. "Panton-Valentine-Leucocidin, a virulence factor implicated in necrotic staphylococcal pneumonia, induces inflammasome upregulation and IL-1β release in human alveolar macrophages." (PMID 23840534, 2013). "It has been reported that bacterial hemolysins, for example, listeriolysin O of Listeria monocytogenes, hemolytic cytolysin pneumolysin of Staphylococcus pneumonia and hemolysin of S. aureus, can induce the release of IL-1β through activation of NLRP3 inflammasome." (PMID 26052324, 2015).
stress-related disorder (2 papers, 2019 to 2021). Stress-related disorders are mental health disorders that are a result of an atypical response to both short and long-term anxiety due to physical, mental, or emotional stress. "It is reported that increased releases of proinflammatory cytokines such as TNF-α and IL-1β commonly appeared in individuals with stress-related disorders, and the present results revealed that SHXXD could suppress the overexpressed proinflammatory cytokines of TNF-α and IL-1β." (PMID 31178969, 2019).
substance abuse (2 papers, 2021 to 2025). The use of a drug for a reason other than which it was intended or in a manner or in quantities other than directed. "Neuroinflammation, characterized by microglial activation and increased pro-inflammatory cytokines (such as IL-1β, IL-6, and TNF-α), is a potential mechanism behind the behavioral changes observed in individuals exposed to chronic stressors and substance abuse." (PMID 40563776, 2025).
sweet syndrome (2 papers, 2019 to 2023). "The finding of a somatic mutation that confers sensitivity to IL-1β demonstrates that Sweet syndrome may be caused by a cell-intrinsic process." (PMID 36355435, 2023). "Among the seven other patients with Sweet syndrome, 3 exhibited a similar increase in IL1B transcript levels in their microarray compared with those of healthy controls (yellow box)." (PMID 36355435, 2023). "Taken together, these data suggested a role for IL-1β production in a subset of patients with Sweet syndrome, including our index patient." (PMID 36355435, 2023). "In our patient with refractory Sweet syndrome, the return of clinical symptoms when pausing anakinra confirmed that her circulating neutrophils had a permanent sensitivity to IL-1β." (PMID 36355435, 2023).
T cell lymphoma (2 papers, 2024). "The role of TIM-3 deficiency, high IL-1β production and hyperinflammation were previously studied among patients suffering from SPTCL, a rare form of T cell lymphoma, which can be complicated by HLH." (PMID 38485795, 2024). "Downregulation of IL1B was detected in advanced stage of T-cell lymphoma." (PMID 39588389, 2024).
thrombotic disease (2 papers, 2016 to 2021). The formation of a blood clot in the lumen of a vessel or heart chamber; causes include coagulation disorders and vascular endothelial injury. "LiC has been widely used in the treatment of thrombotic diseases and can reduce the levels of pro-inflammatory cytokines (IL-1β, TNF-α)." (PMID 34992529, 2021). "The levels of cleaved caspase-1, IL-1β and cleaved IL-1β in AF(+)Thrombus(+) patients were significantly higher than those with sinus rhythm, and were elevated when compared with AF(+)Thrombus(-) patients." (PMID 26930272, 2016).
tongue cancer (2 papers, 2021 to 2023). A malignant neoplasm affecting the tongue. "The extract significantly reduces the expression of pro-inflammatory molecules s100a9, interleukin 23 subunit alpha (IL23a), interleukin 1 beta (IL1β) and immune checkpoint gene PDCD1/programmed cell death-1 (PD1) during tongue cancer prevention." (PMID 34765739, 2021).
tongue squamous cell carcinoma (2 papers, 2015 to 2020). A squamous cell carcinoma that arises from the tongue. "We measured the effect of IL-1β on CXCR4 expression in human tongue squamous cell carcinoma Tca8113 cells." (PMID 26176534, 2015). "The dataset (38 patient samples) exhibited IL-1B (p = 2.67 × 10−6), TGF-β2 (p = 2.23 × 10−4), and MMP9 (p = 0.01) genes to be upregulated in tongue squamous cell carcinoma (SCC) compared with normal tongue tissue." (PMID 32961854, 2020).
tongue tumor (2 papers, 2022). "We validate the association of Fusobacterium with the inflammatory markers IL1B, IL6 and IL8, miRNAs hsa-mir-451a, hsa-mir-675 and hsa-mir-486-1, and MMP10 in the tongue tumor samples." (PMID 35252868, 2022). "To further validate the association between Fusobacterium burden and inflammation, we evaluated the levels of pro-inflammatory cytokines IL1B, IL8 and IL6 in Fusobacterium-high and -low in-house early-stage tongue tumor samples (n = 75)." (PMID 35252868, 2022).
tonic-clonic seizures (2 papers, 2014 to 2024). "The effect of sertraline at doses within the range of 0.75 to 25 mg/kg on the increase in IL-1β and TNF-α mRNA expression accompanying generalized tonic-clonic seizures, and increase in the pro-inflammatory cytokines expression induced by lipopolysaccharide was also investigated." (PMID 25364907, 2014).
tuberculosis meningitis (2 papers, 2018 to 2023). "Similarly, we also observed a significant increase in the expression of IL-1β in the brain of the mouse model for tuberculosis meningitis." (PMID 37894158, 2023).
typhoid fever (2 papers, 2014 to 2025). A bacterial infectious disorder contracted by consumption of food or drink contaminated with Salmonella typhi. "This view is consistent with the clinical observation that serum levels of pyrogenic cytokines IL-1β and TNF-α are relatively low in patients with typhoid fever compared to the levels found in patients with sepsis caused by other Gram-negative pathogens." (PMID 25136336, 2014). "In fact, IL-1β and TNF-α production by PBMCs has been shown to be suppressed during the acute phase of typhoid fever." (PMID 25136336, 2014).
uremia (2 papers, 2021). A clinical syndrome associated with the retention of renal waste products or uremic toxins in the blood. "Uremic toxins from BiNx serum amplified the expression of iNOS, IL-1β, and TNF-α, supporting uremia-induced proinflammatory macrophages." (PMID 33436518, 2021).
uveal melanoma (2 papers, 2020 to 2023). A melanoma derived from melanocytes of the uveal tract. "Here, we show that NLRP3 and IL‐1β levels in uveal melanoma are minimal." (PMID 36707938, 2023).
vaginitis (2 papers, 2011 to 2025). A non-infectious or infectious inflammatory process affecting the vagina. "Previous studies have shown that proinflammatory cytokines such as TNF-α, IL-1β, and IL-6 are increased in the vagina of women with vaginitis and are associated with the severity of vaginitis." (PMID 39941110, 2025).
ventricular tachycardia (2 papers, 2022 to 2023). A disorder characterized by an electrocardiographic finding of three or more consecutive complexes of ventricular origin with a rate greater than a certain threshold (100 or 120 beats per minute are commonly used). "Along with TNF and IL-6, IL-1 (not mature IL-1β) was indicated as a factor involved in delayed repolarization, long QT syndrome, and ventricular tachycardia." (PMID 36341442, 2022).
Wolfram syndrome (2 papers, 2021 to 2022). Wolfram syndrome (WS) also known as DIDMOAD, is a neurodegenerative disorder characterized by type I diabetes mellitus (DM), diabetes insipidus (DI), sensorineural deafness (D), bilateral optical atrophy (OA) and neurological signs. "We have previously shown that dantrolene sodium reduces serum IL-1β levels in patients with Wolfram syndrome." (PMID 35399956, 2022). "As compared with levels previously reported in heathy subjects, levels of IFN-γ, TNF-α, IL-1β, MIP-1β, MIP-3α, IL-21, and isoprostane were higher in study subjects with Wolfram syndrome." (PMID 34185708, 2021). "As previously reported, markers of inflammatory cytokines and oxidative stress, such as IFN-γ, IL-1β, TNF-α, and isoprostane, were elevated in subjects with Wolfram syndrome." (PMID 34185708, 2021).
absence seizures (1 paper, 2015). "Unfortunately, no data are available on the levels of IL-1β in humans before or after the onset of absence seizures." (PMID 24609207, 2015).
Acanthamoeba infection (1 paper, 2025). "Investigating chronic infection models will help determine the long-term role of macrophages and IL-1β in immune regulation, parasite persistence, and tissue pathology, providing new insights into chronic Acanthamoeba infections." (PMID 40109888, 2025). "In Acanthamoeba infections, despite multiple potential sources of IL-1β including neutrophils, dendritic cells, and epithelial cells, the overall secretion remains low." (PMID 40109888, 2025). "In addition, the differential regulation of autophagy- and inflammasome-related pathways highlights multiple mechanisms involved in IL-1β secretion during Acanthamoeba infection." (PMID 40109888, 2025). "Similarly, our study suggests that Acanthamoeba infection results in remarkably low IL-1β secretion, potentially due to its ability to modulate macrophage autophagy, which in turn prevents efficient inflammasome activation and cytokine release." (PMID 40109888, 2025). "Several cytokines, for example, IFN-γ, IL-4, IL-10, IL-17A, IL-17F, and IL-22, were reported to rapidly produce and secrete in response to the Acanthamoeba infection but not IL-1β cytokine." (PMID 40109888, 2025).
Acanthamoeba keratitis (1 paper, 2022). Keratitis due to infection by acanthamoeba; it is usually associated with soft contact lens wear, particularly overnight wear. "SNPs in IL1B (rs16944), CXCL8 (rs2227307, rs2227543, and rs1126647), and IL22 (rs1179251) have been associated with decreased risk of severe inflammatory complications during Acanthamoeba keratitis." (PMID 36422638, 2022).
acute cholecystitis (1 paper, 2025). "Higher levels of biliary IL-1β are found in patients with acute cholecystitis." (PMID 40003307, 2025).
acute monocytic leukaemia (1 paper, 2017). "Similarly, silver wires induced ROS generation, lysosomal rupture, cathepsin B, caspase-1 and IL-1β production in human acute monocytic leukaemia (THP-1) cells." (PMID 28250714, 2017).
acute pharyngitis (1 paper, 2025). An acute and painful inflammatory process that affects the pharynx. "In the experimental studies assessing the pharmacological effects of KHJ on acute pharyngitis before and after compatibility, all drug groups exhibited significant reductions in serum IL-1β, IL-6, and PGE2 levels, besides a notable increase in IL-10 levels." (PMID 41357871, 2025). "IL-6 activates mononuclear macrophages and impacts immune responses, whereas IL-1β overexpression causes tissue damage, edema, and exacerbate responses in rats with acute pharyngitis through interactions with TNF-α and IL-6." (PMID 41357871, 2025).
acute rhinitis (1 paper, 2017). "CD11b- and Iba-1-positive cells that infiltrated the OM produced IL-1β in response to acute rhinitis." (PMID 28912588, 2017).
acute T-cell leukemia (1 paper, 2015). "Cho etal. also reported that PYC inhibited expression of IL-1β mRNA in RAW264.7 cells and IL-2 expression in JurlatE6.1 cells, a human acute T-cell leukemia cell line, through different mechanisms." (PMID 26367267, 2015).
adenoid hypertrophy (1 paper, 2022). "Furthermore, prior works showed that the MBL2 (SNP 49 C/T rs5030737) gene polymorphism; the AG + GG and AG genotypes at TLR4-D299G; Ugrp2; and the 2R, 2R, Il-1Ra and T, and T IL-1b genotypes were associated with an increased risk of developing adenoid hypertrophy." (PMID 35207552, 2022).
adenovirus infection (1 paper, 2022). "A fowl adenovirus, known to cause severe disease in poultry populations, induced elevated mRNA transcription for the same spectrum of pro-inflammatory cytokines detected following mouse and human adenovirus infection (IL-1β, IL-6, IL-8, IFN-α, IFN-β, IFN-γ)." (PMID 35632630, 2022). "In summary, the cytokines and chemokines released in response to adenovirus infection are pro-inflammatory in nature and include cytokines IL-1α, IL-1β, IL-6, IL-8, IFN-γ, IFN-α, and TNF-α and chemokines CCL2, CCL3, and CXCL10." (PMID 35632630, 2022).
adrenal adenomas (1 paper, 2019). "Studies in human adrenal adenomas led to propose the existence of an alternative pathway of GC synthesis governed by IL-1β and IL-1RI, instead of ACTH." (PMID 31998227, 2019).
adrenal hyperplasia (1 paper, 2023). "Additionally, IL-1b was suggested to be the most potential diagnostic biomarker to discriminate the APA and unilateral adrenal hyperplasia (UAH)." (PMID 37029172, 2023).
adrenocortical insufficiency (1 paper, 2025). An endocrine or hormonal disorder that occurs when the adrenal cortex does not produce enough of the hormone cortisol and in some cases, the hormone aldosterone. "In pediatric populations (<18 years), secondary adrenocortical insufficiency (ROR: 7.09, 95% CI = 2.6–19.35) was more prevalent, likely due to immature immune-endocrine crosstalk—IL-1β is a critical mediator of stress-induced cortisol release in children, and its inhibition may disrupt this axis." (PMID 41471316, 2025).
Ageusia (1 paper, 2023). A rare condition that is characterized by a complete loss of taste function of the tongue. "The serum concentrations of inflammatory markers (IL-1β, TNF-α, and CRP) were higher in subjects with ageusia/hypogeusia than in subjects with normogeusia, but without any statistical significance." (PMID 36675526, 2023).
alexithymia (1 paper, 2021). An agnosia that is a deficiency in understanding, processing, or describing emotions. "Lymphocyte subset counts (CD4, CD8), in vitro production of interleukin 1β (IL-1β), IL-2, IL-4, and IL-10 by phytohemagglutinin stimulated peripheral blood lymphocytes, as well as serum cortisol levels, were compared between women with and without alexithymia." (PMID 34987425, 2021).
algodystrophy (1 paper, 2022). "Patients with algodystrophy present an amplified and persistent activation of the innate immune system, with subsequent proliferation of keratinocytes and release of proinflammatory cytokines including interleukin (IL)-6, IL-1β, and tumor necrosis factor-α (TNF-α)." (PMID 36120194, 2022).
alopecia totalis (1 paper, 2023). Alopecia totalis is a form of alopecia areata, an inflammatory disease of the hair follicle, characterized by a complete loss of hair of the entire scalp which becomes glabrous. "Polymorphisms in the IL‐1RA gene/‐s have been linked to an increased predisposition to the more severe forms of AA; alopecia totalis and universalis, indicating a reduced ability to control IL‐1α and IL‐1β signalling." (PMID 37275428, 2023).
altitude sickness (1 paper, 2023). Multiple symptoms associated with reduced oxygen at high altitude. "Plasma levels of IL-1β, IL-6, and TNF-α were found to be increased in individuals with altitude sickness compared to controls in low-altitude environments." (PMID 36891263, 2023).
ameloblastoma (1 paper, 2022). The most common odontogenic tumor, arising from the epithelial component of the embryonic tooth and usually affecting the molar-ramus region of the mandible or maxilla. "Several studies reported that some cytokines were secreted from ameloblastoma cells, including IL-1α, IL-1β, IL-6, and TNF-α." (PMID 35243014, 2022).
Anal fistula (1 paper, 2016). An abnormal connection between the epithelialised surface of the anal canal and the perianal skin. "Based on our previous study, it seems likely that peptidoglycan is a one of the potential stimuli for the expression of IL-1β in anal fistulas." (PMID 27402195, 2016). "The key finding of the present study was the abundant expression of pro-inflammatory cytokine IL-1β in 93 % of the anal fistulas." (PMID 27402195, 2016). "The objective of the present study was to assess local production of a selected panel of cytokines in anal fistulas, including pro-inflammatory interleukin (IL)-1β and tumor necrosis factor α (TNF-α)." (PMID 27402195, 2016). "Frequencies of IL-1β-producing cells were highest (>50 positive stained cells) in 7 % of the anal fistulas." (PMID 27402195, 2016). "IL-1β is expressed in the large majority of cryptoglandular anal fistulas, as well as several other pro-inflammatory cytokines." (PMID 27402195, 2016). "The key finding was abundant expression of IL-1β in 93 % of the anal fistulas." (PMID 27402195, 2016). "Pro-inflammatory IL-1β is expressed in the large majority of cryptoglandular anal fistulas." (PMID 27402195, 2016).
anal prolapse (1 paper, 2022). "Reduces anal prolapse, surrounding hyperemia by decreasing MPO activity, serum IL-1β, IL-6, TNF-α levels, and increasing IL-4, IL-10 levels." (PMID 35548468, 2022).
ANCA-associated vasculitis (1 paper, 2024). "In this study, we explored the levels of IL-18 and IL-1β in serum and urine and the influence of various single-nucleotide polymorphisms (SNPs) on kidney lesions at diagnosis in patients with ANCA-associated vasculitis (AAV) and their clinical outcomes." (PMID 38928186, 2024).
Anosmia (1 paper, 2023). An inability to perceive odors. "This improvement was associated with a downregulation of IL-1β and IL-6 mRNA in the brain ́s prefrontal cortex, and it was impaired by anosmia induction with methimazole." (PMID 37187754, 2023).
anovulation (1 paper, 2025). The absence of ovulation. "Moreover, increased levels of IL-1β may also be the result of anovulation in women with PCOS." (PMID 40647668, 2025).
anterior uveitis (1 paper, 2023). Inflammation of the iris and anterior chamber of the eye. "A slight upregulation of the IL1β and downregulation of IL6, IL4, and CD11b further confirmed a basal complement activation in the blood of patients with anterior uveitis." (PMID 38187376, 2023).
anxiety-depression (1 paper, 2013). "The levels of IL-1β and IL-10 in the sigmoid colon mucosal membranes and blood of the anxiety-depression IBS-D group were significantly different from those of the non-anxiety-depression IBS group." (PMID 23935726, 2013). "The levels of IL-1β in the blood and sigmoid colon mucosa in the anxiety-depression IBS-D group (21.65±0.78 and 20.86±1.34, respectively) were significantly higher than those in the non-anxiety-depression IBS-D group (18.35±1.37 and 16.28±0.97, respectively; P<0.05)." (PMID 23935726, 2013).
aortic valve disease (1 paper, 2011). "Our results show that elevated pressure induces a gene expression pattern in cells that is considerably similar to that seen in aortic valve disease, in terms of altered expression of ECM proteins (MMP-1, MMP-3) and proinflammatory cytokines (IL-1β, IL-6)." (PMID 21876831, 2011).
aortic valve stenosis (1 paper, 2019). Aortic valve stenosis (AVS) is a condition characterized by narrowing of the heart's aortic valve opening. "Monocytes secrete IL-1β, a potent pro-inflammatory cytokine, which is implicated in multiple pathologies including aortic valve stenosis; interestingly IL-1β and monocytes have not been found in the normal aortic valves." (PMID 31510085, 2019).